KEAP1 (kelch like ECH associated protein 1)
Diseases named in the same sentence as KEAP1 in open-access papers (continued):
Sharing a sentence is not in itself a finding about the gene and the disease.
lung carcinoma (continued). "PSAT1 is a known target in NFE2L2/KEAP1 mutant lung cancer cell lines and was elevated in lung cancer and PDX tissues compared to adjacent lung tissues, suggesting serine biosynthesis could be an attractive target in SCC30,43." (PMID 31395880, 2019). "Interestingly, overexpression of miR-421 reduced the level of KEAP1 expression, which further promoted lung cancer cell migration and invasion, as well as inhibited cell apoptosis both in vivo and in vitro." (PMID 31659154, 2019). "Stratification of the lung cancer cases based on our NRF2 activation identifier revealed a large number of cases appeared to have NRF2 activation yet did not harbor an NRF2 or KEAP1 mutation." (PMID 30150714, 2018). "Likewise in lung cancer, deletion of KEAP1 promotes cancer aggressiveness, metastasis and resistance to oxidative stress as produced by radiotherapy." (PMID 29719593, 2018). "We thus aim to explore whether autophagy regulates vinorelbine sensitivity through Keap1/Nrf2-mediated ROS generation in lung cancer cells." (PMID 30245856, 2018). "Notably, these top 2 GO enrichment results also further support KEAP1/NRF2-mediated metabolic protein regulation in lung cancer." (PMID 29050246, 2017). "Although KEAP1/NRF2 alterations are known to confer resistance to chemotherapy, KEAP1/NRF2 mutation status is not used to make treatment decisions in lung cancer." (PMID 28145866, 2017). "For instance, there are compelling evidences that epigenetic regulation might play a key role in modulating Keap1/Nrf2 axis in lung cancer cells." (PMID 27847554, 2016). "Mutations and copy number alterations of NFE2L2 and KEAP1 and/or deletion or mutation of CUL3 were observed in 25–34% of SqCC among the classical alterations associated with this smoking-related histology subtype of lung cancer." (PMID 27847554, 2016). "This is consistent with results from a recent study where 4 of 18 KEAP1 mutations identified in lung cancer specimens did not impair the ability of KEAP1 to promote NRF2 degradataion." (PMID 26301506, 2015). "Furthermore, several KEAP1 mutations that were identified in lung cancer specimens differentially affect binding of NRF2 and IKKβ to KEAP1." (PMID 26301506, 2015). "We have previously reported the somatic mutations of the NRF2 gene (NFE2L2), however, the correlation between the Keap1 mutation and the clinicopathological features of lung cancer has not been well investigated." (PMID 24137397, 2013). "A study of Japanese lung cancer patients (AC, SCC, large cell carcinomas (LCCs), and SCLC) documented these KEAP1 mutations and identified them as a source of constitutive expression of MDR proteins, phase II enzymes as well as specific cisplatin resistance in cultured lung AC cells." (PMID 23577226, 2013). "In addition, the expression of Keap1 has been reported to be regulated by DNA methylation in lung cancer." (PMID 20062804, 2010). "Notably, similar pattern of specific methylation of the distal CpG island has also been observed in the Keap1 gene in lung cancer cells." (PMID 20062804, 2010). "Interestingly, by hypermethylation of the Keap1 promoter, an epigenetic mechanism, Keap1 expression was reduced in lung cancer cell lines and tissues, compared to that in normal bronchial epithelial cell line." (PMID 24281078, 2010). "Similarly, Duan and coworkers demonstrated that miR-421 overexpression in A549 lung cancer cells directly targeted 3′-untranslated region (3′UTR) of KEAP1 gene, leading to its downregulation with an increased proliferation and invasion but decreasing apoptosis process." (PMID 40563292, 2025). "Moreover, in lung cancer BAP1 is tumor‐suppressive by inhibiting the KEAP1/NRF2 signaling pathway." (PMID 40600748, 2025).
lung carcinoma (continued). "Since KEAP1 negatively keeps the basal protein levels of NRF2 through the KEAP1-Cul3-RBX1 E3-ubiquitin ligase complex (see chapter 3.2), somatic mutations of KEAP1 abolish this protein-protein interaction with NRF2 and lead to NRF2 activation, which is targetable in lung cancer therapy." (PMID 38908072, 2024). "YEATS4 amplification samples show increased mRNA levels of several well-known antioxidant genes, including NQO1, SLC7A11, and GCLC, suggesting beside NFE2L2 mutation and KEAP1 mutation, YEATS4 amplification could be the other critical genetic marker in lung cancer by modulating antioxidant pathways." (PMID 38514704, 2024). "However, research has found that the lack of KEAP1 promotes the dependency of lung cancer cells on glucose, and KEAP1-mutated/deficient lung cancer cells are more sensitive to glucose deprivation than their wild-type counterparts." (PMID 39744129, 2024). "Given that canonical metabolic drugs may also harm normal cells, the combination of AURKA inhibitors with L-asparaginase, as reported in a recent study for KEAP1 mutant lung cancer, holds promise for achieving enhanced therapeutic efficacy and merits further investigation." (PMID 38521813, 2024). "Additionally, it has been reported that the transcription factor stimulating protein-1 (SP1) exhibited impaired binding to the promoter of KEAP1 in A549 lung cancer cells compared to normal bronchial epithelial cells, potentially attributed to the hypermethylation of the KEAP1 promoter." (PMID 39061847, 2024). "A recent genomic analysis of a large G12C mutant lung cancer cohort treated with G12C inhibitors revealed that co-occurring mutations of KEAP1, SMARC4 and CDKN2A were independent negative predictive factors of inhibitor efficacy while mutations in the DDR genes were positive predictive ones." (PMID 38239281, 2023). "Hence, targeting SIRT6 might be a new promising epigenetic therapeutic approach to evade Nrf2/Keap1-powered cellular rescue pathways in lung cancer." (PMID 38235110, 2023). "STK11 and KEAP1 mutations do not seem to influence the prognosis in KRAS wildtype lung cancers." (PMID 38067288, 2023). "Notably, 4-CBA treatment did not affect RT-induced lipid peroxidation and had no radiosensitizing effect in HBECs, suggesting that 4-CBA might selectively affect KEAP1 mutant lung cancer cells while sparing normal lung epithelial cells." (PMID 35459868, 2022). "It has also been found that Keap1/Nrf2 mutation status predicts the risk of local recurrence after radiotherapy in NSCLC patients, and Keap1/Nrf2 mutant lung cancers may be radiotherapy resistant to radaition due to enhanced expression of ROS clearance and detoxification pathways." (PMID 36589232, 2022). "In addition, by analyzing the TCGA human lung cancer dataset, we found that the advanced‐stage tumors (clinical stage IV disease) were significantly enriched for the human KEAP1‐mutant transcriptional signature, and core SOX9 target genes were significantly upregulated in tumors from advanced stage." (PMID 33173725, 2020). "However, the correlation between KEAP1 mutations and DNA methylation in lung cancer has still not been investigated." (PMID 32327612, 2020). "Besides, other mechanisms, such as epigenetic hypermethylation of the promoter of Keap1, may also contribute to the accumulation and activation of Nrf2 in lung cancer." (PMID 33324555, 2020). "Therefore, targeting miR-421/KEAP1 could be a potential strategy for the treatment of paclitaxel-resistant lung cancer patients." (PMID 31659154, 2019). "The selective inhibition of KEAP1 gene promoter methylation by genistein, observed in A549 cells, suggested a way in which KEAP1 demethylation could represent a marker of radio-sensitizing effects in lung cancer." (PMID 31159323, 2019).
lung carcinoma (continued). "Given the critical role of KEAP1 in several other cancer types, we decided to investigate the clinical relevance of KEAP1 expression in clinical lung cancer tumours, and we detected the protein level of KEAP1 in lung cancer patient samples by the immunohistochemical method." (PMID 31659154, 2019). "In lung cancer, the presence of epigenetic abnormalities in the KEAP1 gene plus its point mutations/LOH matched with the prevalence of NRF2 nuclear accumulation in NSCLC tissues and was associated with an increased risk of lung cancer progression in surgically resected patients." (PMID 29643973, 2018). "As more patients are treated with RTK/MAPK inhibitors, analyzing KEAP1 and NRF2 status in pre-treatment and post-resistance tumor samples will determine if loss of KEAP1 or gain of NRF2 are clinically relevant mechanisms of acquired and intrinsic resistance to these therapies in lung cancer." (PMID 28145866, 2017). "Thus, while these studies are not lung-specific, they demonstrate that NRF2 and KEAP1 mutations identified in human lung cancer have functional effects in animal models." (PMID 23577226, 2013). "The Keap1 mutation was only detected in patients with advanced adenocarcinoma (4.3%) and the completely exclusive status of this mutation and others, including EGFR, Kas, erbB2 and NRF2L2, is likely to improve the selection of personalized therapy for lung cancer." (PMID 24137397, 2013). "To test this, we used the well-validated KEAP1 inhibitors SFN, CDDO and KI-696, the BACH1 inhibitor TBE56 and the dual KEAP1/BACH1 inhibitor CDDO-TFEA in the lung cancer cell line H1299." (PMID 40716152, 2025). "KEAP1 negatively regulates the cytoprotective factor NRF2 and is commonly inactivated in lung cancer cells." (PMID 41462606, 2025). "In lung cancer molecular subtyping, the LKB1/KEAP1 double‐mutant subtype exhibits unique metabolic dependencies." (PMID 40919133, 2025). "We chose the lung cancer cell line H1299 for these experiments due to its high BACH1 levels and functional KEAP1 (leading to low NRF2 levels), making it an ideal model for studying both BACH1 and KEAP1 depletion." (PMID 40716152, 2025). "KEAP1 loss-of-function (LOF) and NFE2L2 gain-of-function (GOF) mutations exhibited a mutually exclusive pattern, demonstrating that the overexpression of NRF2 may contribute as pivotal mechanism in the selection of specific cancers or stages of tumor progression, including lung cancer." (PMID 40563292, 2025). "In lung cancer, PTMs orchestrate critical pathological processes, such as EGFR phosphorylation-driven proliferation, H3K27me3-mediated epigenetic silencing, and KEAP1 succinylation-regulated redox homeostasis." (PMID 41306527, 2025). "For instance, NESTIN relies on its own ESGE motif (amino acids 1412–1422) to competitively bind KEAP1 and promote NRF2 protein upregulation, contributing to malignant progression in non‐small cell lung cancer." (PMID 40583858, 2025). "Here, we use an antigenic orthotopic lung cancer mouse model and patient-derived xenografts (PDXs) to investigate the impact of DRP-104 on KEAP1 mutant lung tumor growth." (PMID 38536921, 2024). "After analyzing 12,478 samples / 9,930 patients with lung cancer from 29 studies, it was found that the total variation in NRF2 and KEAP1 genes was 4% and 13%, respectively." (PMID 38169561, 2024). "Here, using preclinical patient-derived xenograft models and antigenic orthotopic lung cancer models, we show that the glutamine antagonist prodrug DRP-104 impairs the growth of KEAP1 mutant tumors." (PMID 38536921, 2024). "In aggregate, we have shown that KEAP1 mutants R320Q and R470C interact with TRAF2 resulting in its stabilization and activation of NFκB in lung cancer cells." (PMID 38184997, 2024).
lung carcinoma (continued). "Interestingly, recent research has revealed that the activation of NRF2, achieved by inhibiting KEAP1, can reduce the viability of several lung cancer cell lines, suggesting that high NRF2 activity may lead to cell death and sensitize cancer cells to chemotherapeutic agents." (PMID 38247494, 2024). "We selected three (KL/K)MUT and three (KL/K)WT lung carcinoma cell lines for further study: The first group included HCC44 and H460 (KRAS/LKB1/KEAP1 triple mutant) along with H1792 (KRAS/KEAP1 double mutant)." (PMID 38949950, 2024). "In targeted therapy, R16, a small-molecule agent, bound to mutant KEAP1 and reversed its ability to inhibit NRF2, thereby sensitizing lung cancer cells to gefitinib." (PMID 39061847, 2024). "The results indicate that R320Q and R470C mutants of KEAP1 increase S11 phosphorylation and stability of TRAF2, leading to activation of NFκB in lung cancer cells." (PMID 38184997, 2024). "Our data suggest that NMT1 is a potential therapeutic target in lung carcinomas with mutant KRAS and LKB1 and/or KEAP1 (KL/K)MUT, which are highly aggressive and resistant to current therapies, including immune checkpoint inhibitors." (PMID 38949950, 2024). "Deletion of both KEAP1 and PTEN was shown to result in decreasing number of NK cells in mice with lung cancer." (PMID 36632216, 2023). "In lung cancer cells, CDK20 can compete with Nrf2 to bind to Keap1, enhance the transcriptional activity of Nrf2 and reduce the level of ROS, thereby promoting the continuous proliferation of cancer cells." (PMID 37810967, 2023). "Our study demonstrates that both CDDO-TFEA and CDDO-Me are very potent dual KEAP1 and BACH1 inhibitors, and that they reduce lung cancer cell invasion in a BACH1-dependent and NRF2-independent manner." (PMID 35313207, 2022). "We found eight genes relevant to lung cancer (PDGFRB, RET, KRAS, KEAP1, ROS1, STK11, MET and ALK), for which integrating clinical data with our TME features clearly improves the ability to predict mutations in these genes." (PMID 36131239, 2022). "We also observed that KEAP1 deubiquitination by BAP1 stabilizes KEAP1, suppresses NRF2 target genes, and promotes oxidative stress, thereby interfering with the growth of lung cancer cells." (PMID 35052618, 2022). "Analysis of IMPOWER 150 also presented that, for the subgroup of patients with KRAS-mutant lung cancer carrying STK11 and/or Keap1 simultaneously, Atezolizumab combined with Bevacizumab and chemotherapy is an effective first-line treatment." (PMID 35887766, 2022). "Contrarily, NRF2 is overexpressed as a result of excessive KEAP1 deletion and PI3K/Akt activation in lung cancer, which results in the resistance to oxidative stress and causes uncontrollable proliferation and metastasis of tumor cells." (PMID 34277453, 2021). "In addition, the exon 2 in the Nrf2 locus is recurrently lost via alternative splicing and this contributes to the production of NRF2 isoform lacking the Neh2 domain, suggesting an alternative mechanism how NRF2 is activated in lung cancer cells that do not bear mutations in the KEAP1/NRF2 pathway." (PMID 34566633, 2021). "CUL3 plays an important role in ubiquitination of KEAP1, a negative regulator of the transcription factor NRF2 which enacts a transcriptional program important in protecting lung cancer and other tumor types from oxidative stress." (PMID 33435458, 2021). "Collectively, we propose that triptolide has an advantage compared with other NRF2 inhibitors in that it downregulates the expression of NRF2 target genes without affecting NRF2, which could be used to treat lung cancer cells regardless of mutation status in the Keap1/Nrf2 pathway." (PMID 34566633, 2021).
lung carcinoma (continued). "Next, we further detected the expression levels of Keap1 protein in human lung cancer cell lines and human bronchial epithelial HBE cell line by western blot analysis and founded that lower expression of Keap1 in all cancer cell lines compared to HBE." (PMID 34466284, 2021). "Given the critical oncogenic role of SOX9 and the high frequency of KEAP1 mutations in lung carcinoma and HCC, our study suggests an optimal treatment strategy based on genetic status, which may provide stratified clinical treatments for individual lung carcinoma or HCC patients." (PMID 33173725, 2020). "Next, we explored the physiological roles of degron‐mediated SOX9 degradation by KEAP1 in HCC and lung carcinoma." (PMID 33173725, 2020). "Biallelic inactivation of KEAP1, resulting in NRF2 hyperactivation, was identified as a relatively common event in lung cancer." (PMID 32938017, 2020). "KEAP1 dysfunction and increased NRF2 accumulation in the nucleus have been frequently reported in lung cancer." (PMID 32327612, 2020). "KEAP1 silencing by promoter methylation is widely reported in solid tumors as part of the complex regulation of the KEAP1/NRF2 axis, but its prognostic role remains to be addressed in lung cancer." (PMID 31159323, 2019). "Additional research further expanded the list of KEAP1 mutations in several cohorts of patients with different subtypes of lung cancer, pointing out the existence of widely distributed alterations beyond the DGR and the IVR motifs of the KEAP1 protein." (PMID 31097977, 2019). "We focused our analysis on lung cancer, both LUSC and LUAD, since these are the tumor types with the most NRF2 and KEAP1 mutant cases." (PMID 30150714, 2018). "To extend their findings, here we used microarray data from both KEAP1-overexpressing and NRF2-KD A549 NSCLC cells to systematically identify an NRF2-regulated gene signature specifically in lung cancer using multi-omics approach." (PMID 29050246, 2017). "Though KEAP1/NRF2 dysregulation has been considered as an adaptive response that might particularly affect later stages of oncogenesis, recent data in mouse models of pancreatic and lung cancer, where Nrf2 ablation was associated with reduced cellular proliferation, have suggested an early effect." (PMID 22014577, 2011). "However, a recent study found that experimentally implanted lung cancer cells (Lewis lung carcinomas) produced significantly more pulmonary metastatic nodules in Nrf2-/- than in Nrf2+/+mice, while the metastatic nodule formation was suppressed in Keap1-knockdown mice compared to Keap1 normal mice." (PMID 22039513, 2011). "To determine whether NRF2-activated KEAP1-mutant cancer responds to triterpenoid therapies, we employed a murine flank tumor model of CRISPR-edited lung cancer." (PMID 41462606, 2025). "WT, KEAP1 KO, or NRF2 KO lung cancer lines all formed tumors in the lungs." (PMID 38542481, 2024). "Using our recently developed antigenic orthotopic lung cancer model, we revealed that DRP-104 not only is effective in targeting Keap1 mutant lung tumors but also, in combination with checkpoint blockade DRP-104, led to significantly enhanced survival of mice compared to monotherapy." (PMID 38536921, 2024). "A recent investigation unveiled the CoQ-FSP1 axis as a pivotal mechanism driving both ferroptosis and resistance to radiation therapy in lung cancers lacking KEAP1 activity." (PMID 39944353, 2024). "In one study on the clinical outcome of pembrolizumab versus chemotherapy in lung cancer patients, it was observed that the treatment outcomes appeared to be comparable irrespective of the presence of STK11, KEAP1, or KRAS mutations." (PMID 38136385, 2023).